CCAT2 (colon cancer associated transcript 2)
Diseases named in the same sentence as CCAT2 in open-access papers (continued):
Sharing a sentence is not in itself a finding about the gene and the disease.
tumor (continued). "Additionally, we emphasize CCAT2’s role as a competitive endogenous RNA (ceRNA) for multiple tumor suppressor miRNAs, such as miR-4496, miR-493, miR-424, miR-216b, miR-23b, miR-34a, miR-145, miR-200b, and miR-143 and the pro-tumorigenic role of the altered regulatory axis." (PMID 34830370, 2021). "Thus, overexpression of CCAT2 might be responsible for the mitigation of the tumor suppression ability of miR-34a, which has been also shown to promote the activation of cellular senescence programs by downregulating the FOXM1 oncogene independent of CCAT2." (PMID 34830370, 2021). "LncRNA CCAT2, identified for the first time in 2013, was found to be highly expressed in CRC, and its abnormal expression can promote tumor growth, metastasis, and chromosome instability." (PMID 38243936, 2024). "Altogether, these results emphasized that Tec inhibits tumor growth and glycolysis in CRC via mediating the lncRNA CCAT2/ miR-145 axis in vivo." (PMID 38243936, 2024). "Microarray analyses revealed several differentially expressed lncRNAs; among them, five novel lncRNAs, TINCR, CCAT2, AOC4P, BANCR, and LINC00857, were detected in tumor tissue samples and pre and post-operative plasma." (PMID 37670949, 2023). "Our findings demonstrate tumor-suppressive functions of lncRNAs CCAT1 and CCAT2 in colorectal liver metastases." (PMID 37347737, 2023). "Collectively our findings demonstrate tumor-suppressive effects of CCAT1 and CCAT2 in colorectal liver metastases." (PMID 37347737, 2023). "Multivariate survival analysis revealed that high tumor grade and low expression of SNCG were predictors of poorer survival outcomes in MBC patients, while low expression of CCAT2 was the only predictor of poor prognosis in NMBC patients." (PMID 36376369, 2022). "The mice were subcutaneously injected with ESC410 cells transfected with oe-NC + sh-NC, oe-CCAT2 + sh-NC, or oe-CCAT2 + sh-TK1, and their tumor volume measured every week." (PMID 34386421, 2021). "c-Myc expression in the tumour was significantly correlated to that of CCAT1 (R2 = 0.23, p < 0.0001) and CCAT2 (R2 = 0.18, p < 0.0001)." (PMID 33432117, 2021). "Our final panel consisted of seven up‐regulated DElncRNAs (CCAT1, CCAT2, H19, HOTAIR, HULC, MALAT1, PCAT1), which were also known as oncolncRNAs and three down‐regulated lncRNAs (MEG3, PTENP1, and TUSC7) as tumor suppressor lncRNAs (tslncRNAs)." (PMID 33094859, 2021). "Targeting CCAT2 in ESCC demands further investigation to better understand its implications on tumor progression and involvement in tumor radioresistance." (PMID 34830370, 2021). "In order to elucidate the effects of CCAT2 and TK1 on the growth of transplanted ESCC tumors in vivo, we conducted subcutaneous tumor xenografts experiments in nude mice." (PMID 34386421, 2021). "Only 23% and 18% of the variability in c-Myc expression in the tumours is attributable to the expression of CCAT1 and CCAT2 respectively." (PMID 33432117, 2021). "Tumor suppressive lncRNAs (GAS5, MEG3, FER1L4 and LINC00672) and oncogenic lncRNAs (CCAT2, BANCR, NEAT1, MALAT1, H19 and Linc-RoR) have been identified as key regulators of the established tumor suppressor or oncogenic pathways in EC." (PMID 30781521, 2019). "Knockdown of CCAT2, FOXCUT, HOTAIR, TUG1 and UCA1 can suppress various aspects of tumor progression." (PMID 29416703, 2018). "More specifically, 4 lncRNAs (CCAT1, CCAT2, HOTAIR, and UCA1) were upregulated, while 2 lncRNAs (MALAT1 and TUG1) and 1 circRNA (CDR1AS) were downregulated in CRC tumor tissues compared to NATs." (PMID 30195762, 2018). "CCAT2 is highly overexpressed in microsatellite-stable CRC and promotes tumor growth and metastasis." (PMID 26637808, 2016). "The association of high MYC expression and increased progression-free survival suggests that these tumor-suppressive functions of CCAT1 and CCAT2 are mediated through their target MYC, a notion that is backed up by further in vitro analyses presented in this study." (PMID 37347737, 2023).
tumor (continued). "The expression of CCAT1 and CCAT2 in both the matched mucosa and the tumours were not significantly correlated to time to metastasis." (PMID 33432117, 2021). "However, the knockdown of CCAT2 inhibited the proliferation and epithelial-mesenchymal transition (EMT) of CC cells in vitro and suppressed tumor growth in vivo." (PMID 34499007, 2021). "Moreover, CCAT2 interacts with TCF7L2 and leads to WNT pathway activation, which subsequently enhances tumor growth and metastasis as well as chromosomal instability." (PMID 33246471, 2020). "The oncogenic role of CCAT2 has been recognized in large part by virtue of an epigenetic mechanism involving its proximity with MYC and acting as a sponge through its interaction with some tumor suppressor miRNAs, such as miR-145 and miR-216b." (PMID 31398859, 2019). "Tumor suppressive lncRNAs (GAS5, MEG3, FER1L4 and LINC00672) and oncogenic lncRNAs (CCAT2, BANCR, NEAT1, MALAT1, H19, Linc-RoR, TUG1, TDRG1 and PCGEM1) may be a few such examples." (PMID 30781521, 2019). "In addition, CCAT2 expression was positively correlated with FIGO stage (P = 0.002), tumor grade (P = 0.006) and distant metastasis (P < 0.001)." (PMID 27283598, 2016). "Nevertheless, integrating the expression of CCAT1 and CCAT2 by the Random Forest classifier did not improve the predictive values of ColoMet19, the mRNA-based predictor for metastasis previously developed on the same series of tumours." (PMID 33432117, 2021). "Interestingly, a risk-SNV rs6983267 also contributes to increased expression of CCAT1; an adjacent lincRNA of CCAT2, through affecting the long-range chromosomal interaction of MYC enhancer or CCAT1 promoter, then results in a cell-cycle regulation and tumor development." (PMID 32523949, 2020). "MYC, miR-17-5p, and miR-20a are up-regulated by CCAT2 through transcription factor 7 like 2 (TCF7L2)-mediated transcriptional regulation and the interaction between CCAT2 and TCF7L2 results in an enhancement in WNT signaling activity, which promotes tumor growth and metastasis in CRC." (PMID 28108736, 2017). "Regarding the relationship with clinicopathological features, the increased expression level of CCAT2 and LOC400891 could be the identifiers of an existence of distance metastasis, tumor diameter (≤ 2.5 vs > 2.5 cm) and histological grade (II vs III + IV) for PCa." (PMID 28915709, 2017). "Considering the role of CCAT2 as an oncogene, these data suggest that it might participate in the early stages of tumor development rather than late stages." (PMID 28480695, 2017). "In addition, we found that CCAT2 relative expression was positively correlated with tumor FIGO stage, SCC-Ag and LNM (all P < 0.05), suggesting that CCAT2 expression level may prove to be an adjuvant marker for monitoring the degree of malignancy and disease progression." (PMID 35115025, 2022). "To further explore this result and identify the tissue localization of CCAT2, we performed in situ hybridization (ISH) employing a locked-nucleic acid (LNA) specific probe for the lncRNA on tissue microarray (TMA), containing 16 non-tumor samples and 18 tumor samples from MDACC." (PMID 24077681, 2013).
colorectal (1 paper, 2023). "Gene expression level analysis with semi-quantitative RT-PCR revealed increased expression of lncRNAs CCAT1 and CCAT2 in colorectal liver metastases compared to adjacent liver tissue." (PMID 37347737, 2023).
CCAT2 also shares sentences with these, for which no sentence is quoted: renal cell carcinoma (3 papers); myelodysplastic neoplasms (2); pancreatic ductal adenocarcinoma (2); small cell lung carcinoma (2); squamous cell carcinoma (2); acute coronary syndrome (1); adenocarcinoma (1); adenoma (1); clear cell renal cell carcinoma (1); colorectal adenoma (1); colorectal tumor (1); digestive system cancer (1); liver cirrhosis (1); metastasis (1); metastatic cancer (1); mucinous adenocarcinoma (1); myeloid malignancies (1); myeloproliferative neoplasm (1); nasopharyngeal carcinoma (1); oral cavity cancer (1); Oral Squamous Cell Carcinoma (1); stomach cancer (1).